MIR5700 (microRNA 5700)
Synonyms: hsa-mir-5700
Gene: MicroRNA gene on chromosome 12 (94,561,789 to 94,561,859, forward strand). Ensembl gene ENSG00000266099.
Homologues: Orthologues: macaque MIR5700 (100% identical).